ASDURF (ASNSD1 upstream open reading frame)
Synonyms: ASNSD1-SEP
Tractability: No criterion of Open Targets' tractability assessment is met for any kind of drug.
Gene: Protein-coding gene on chromosome 2 (189,661,452 to 189,666,437, forward strand). Ensembl gene ENSG00000286053.
Subcellular location: Cytoplasm
Gene Ontology:
Biological process: protein stabilization
Cellular component: cytoplasm; RPAP3/R2TP/prefoldin-like complex
Genetic constraint (gnomAD): Loss-of-function variants: 0 observed, 0.3 expected, observed/expected ratio (o/e) 0, 90% interval 0 to 1.87. That is too few expected variants to judge how well the gene tolerates losing a copy. Missense variants: 8 observed, 7.8 expected, observed/expected ratio (o/e) 1.03, 90% interval 0.6 to 1.74. Synonymous variants: 5 observed, 2.67 expected, observed/expected ratio (o/e) 1.87, 90% interval 0.8 to 1.95.
Homologues: Orthologues: macaque ASDURF (96% identical), rabbit ASDURF (77% identical), dog ASDURF (69% identical), mouse Asdurf (66% identical).